EGF (epidermal growth factor)
Diseases named in the same sentence as EGF in open-access papers (continued):
Sharing a sentence is not in itself a finding about the gene and the disease.
tumor (continued). "Because Neu-YB tumor cells have been shown to express more CXCL12 than the other mutants and Neu-NDL, we investigated whether CXCR4 signaling plays a role in EGF-induced in vivo invasion in that tumor." (PMID 22314082, 2012). "Activation of the PI3K/AKT/GWK3/GS pathway is mediated by some tyrosine kinase receptors, under the control of several growth factors and cytokines as EGF, PDGF, VEGF, TGFbeta, CSF, and especially IGF-I, whose receptor, IGF-I-R, plays a principal role in the tumour growth process." (PMID 22400112, 2012). "The somatic cells of the testes secrete paracrine factors such as SCF, retinoic acid, FGF2, LIF, EGF and GDFN as well as androgenic hormones, and these might play a role in providing a tumor-promoting environment in the mouse." (PMID 22655094, 2012). "In an attempt to verify its potential cancer therapeutic value, SubA was fused to epidermal growth factor (EGF) as a targeting vehicle, and this engineered fusion protein was shown to specifically kill tumor cells overexpressing EGF receptor (EGFR) in vitro and in vivo." (PMID 24278747, 2012). "In this study we found that TGFβ, while it did enhance pII cell invasion, it did so at a relatively high dose as compared with EGF and IGF-1, suggesting that at least its role in tumor invasion and metastasis is subsidiary to its effect as a growth inhibitory agent." (PMID 22860018, 2012). "The finding that both hybrid cells responded to EGF with an increased migratory activity, whereas the parental tumour cell line MDA-MB-435-Hyg did not, indicate the potency of cell fusion in changing the fate of cancer cells." (PMID 22487193, 2012). "For example, MCP-1 and IL-8 levels progressively increased during the course of radiation, while other cytokines, such as IL-4 and EGF were elevated in closer proximity to tumor with no trend for an increase in concentration during the course of radiation." (PMID 22537315, 2012). "Of note, a similar pattern of EGF and p-EGFR expression was observed in LMS stem-like cell-based tumor xenografts, confirming that this experimental model may provide a suitable tool for preclinical testing of EGFR inhibition." (PMID 23056514, 2012). "In addition to EGF, macrophages secrete multiple cytokines including TNF-α and IL-6 suggesting that macrophages in the tumor microenvironment are likely to initiate a signaling network that promotes tumor progression." (PMID 22529912, 2012). "However, in mice with solid sarcoma EGF-SEA, CD4+, CD8+ and SEA-reactive T lymphocytes strongly suppressed tumor growth." (PMID 22375962, 2012). "This is further supported by evidence that tumor cells utilize IGF-1R signaling as a survival mechanism that renders them independent of EGF signals." (PMID 21464922, 2011). "Anti-VEGF (vascular endothelial growth factor) and anti-EGF (epidermal growth factor) and other monoclonal antibodies developed for use in cancer do possess some degree of specific action on tumor cells yet are not very effective." (PMID 21917129, 2011). "Efficiently blocking the interaction between EGF and EGFR could inhibit cell proliferation and tumor growth." (PMID 21687663, 2011). "A small network of downregulated genes was found in tumor cells, in which EGF and beta-c interact with Shc and a complex comprising EGF, ErbB1, Shc-1, Grb2, and Sos (not shown)." (PMID 21464922, 2011). "Following a period of random diffusion, EGF-SEA molecules selectively concentrated in developing tumors that expressed sufficient EGFR, and then retained the passage of T lymphocytes within the tumor site." (PMID 21311755, 2011). "On the other hand, LIV-1 expression may also be stimulated by growth factors in the tumor microenvironment, since treatment with TGFα, TGF-β1, EGF, IGF-1 and β2-M all enhanced the LIV-1 level." (PMID 22110740, 2011).
tumor (continued). "We also assessed whether the stem cell culture cytokines EGF and FGF-2 contribute to differences between stem-like and more differentiated tumor cells in terms of DNA damage levels and of apoptosis resistance upon γ-irradiation." (PMID 21663643, 2011). "The dynamic changes in the levels of EGF-dependent HER1-HER2 heterodimers supported by 2C4 inhibition and erlotinib stabilization were utilized to establish the validity of these measurements in FFPE tumor cell lines." (PMID 21496232, 2011). "In a control of the immunohistochemistry, no labeling was observed in a tumor treated with EGF-SEA using only the goat anti-mouse secondary antibody." (PMID 21311755, 2011). "These chimeric EGF proteins functioned as tumor-targeting molecules, but they were not dependent on antitumor immunocytotoxicity." (PMID 21311755, 2011). "Recalling that EGF was downregulated and IGF-2 was strongly upregulated in tumor cells, the level of IGF-1R dysregulation may represent a switch that marks the onset of malignant transformation." (PMID 21464922, 2011). "Both tumor tissue and normal brain tissue were also stained with control QDs lacking the EGF or primary antibody conjugation or conjugated to non-expressed epitopes and showed no binding." (PMID 20614029, 2010). "The in vitro presence of MSC, MSC-conditioned medium EGF and IL-6 is essential to the growth of tumor cells in a controlled Matrigel environment without the presence of MSC." (PMID 19352430, 2009). "Growth factors stain in patches that do not correlate with the more sparse staining patterns of the TAF markers themselves due to the fact that the tumor cells also secrete the growth factors HGF, IL-6 and EGF in the presence of MSC as demonstrated by in vitro co-culture data." (PMID 19352430, 2009). "While recombinant EGF enhanced Skov-3 proliferation, the immunoprecipitation of EGF from MSC conditioned medium did not significantly effect Skov-3 tumor growth." (PMID 19352430, 2009). "The epidermal growth factor (EGF) gene, which is a member of the EGF superfamily, has been demonstrated to activate cell proliferation and stimulate mitogenesis in epidermal tissue, enhancing tumour growth." (PMID 19624835, 2009). "The 5-year survival of patients with EGF-positive tumours is worse than that of patients with EGF-negative tumours." (PMID 19773760, 2009). "Significantly, EGF induces VEGF, IL-8, and bFGF release by tumor cells." (PMID 18616824, 2008). "Similar expression levels were observed in both conditions for EGF, which may be due to the fact that EGF induces VEGF, IL-8, and bFGF release by tumor cells, and is transformed in the process." (PMID 18616824, 2008). "Both antisense oligonucleotides and siRNA directed against STAT3 limited tumour cell transmigration to below the levels noted in the absence of added EGF." (PMID 16804520, 2006). "In order to identify common growth factor-responsive genes, which may represent candidate genes of tumour growth regulation in general, we compared gene expression induced by gastrin, HGF, EGF and PACAP." (PMID 15846300, 2005). "HRG stimulation promoted physical and functional erbB2/erbB3 interactions and tumor cell growth, whereas no response to EGF or IGF-1 was observed." (PMID 16168116, 2005). "Recent work has shown that tumour cell lines expressing high levels of EGFR may undergo apoptosis, particularly following exposure to EGF." (PMID 15365565, 2004). "Furthermore, epidermal growth factor (EGF) enhanced the co-culture-mediated proMMP-2 activation by increasing the production and gene expression of MT1-MMP, and thereby tumour invasive activity was further augmented." (PMID 10376963, 1999). "This antibody effectively blocks the binding of EGF, transforming growth factor (TGF)-alpha and HB-EGF to the EGFR, inhibits the growth in vitro of tumour cell lines which overexpress the EGFR and eradicates such tumours when grown as xenografts in athymic mice." (PMID 8546911, 1996).
tumor (continued). "There was no statistical difference between either TGF alpha or EGF levels and degree of differentiation of the tumours." (PMID 1764384, 1991). "Both EGF/TGF-alpha-LA and IR-TGF-alpha were detected in 11 tumour cell lines." (PMID 2736210, 1989). "However, as a possible side-effect, the tumor formation potential of these cells must be thoroughly investigated as part of the safety analyses, provided that EGF and FGF2 are also involved in tumor progression due to their proliferative actions on cancer cells." (PMID 40722636, 2025). "It has been shown that M2 macrophages produce growth factors such as epidermal growth factor (EGF), fibroblast growth factor (FGF), and vascular endothelial growth factor (VEGF), which in tumors promote the growth of tumor blood vessels, so that the tumor receives an adequate blood supply." (PMID 39748782, 2025). "After EMT induction and stromal reorganization, tumor cells proceed to intravasate into blood vessels, a step facilitated by a paracrine signaling loop involving tumor-derived CSF1 and macrophage-secreted EGF that directs tumor cell migration toward vasculature." (PMID 41417432, 2025). "Identification of EGF, RHOD, and GAP43 interaction central nodes suggests the disruption of the growth factor signaling, cytoskeletal dynamics, and neuronal differentiation, which could collectively impair tumor progression and metastasis." (PMID 41470892, 2025). "M2 macrophages secrete immunosuppressive and pro-tumorigenic factors, including IL-10, epidermal growth factor (EGF), VEGF, matrix metalloproteinases (MMPs), deoxypyridinoline (DPD), platelet-derived growth factor (PDGF), and TGF-β, thereby facilitating immune suppression and tumor progression." (PMID 40750884, 2025). "Reciprocally, we did not observe the expected increase in tumour number upon >crol-RNAi, which is probably attributed to already strong mitotic stimuli such as EGF signalling acting on Stg and Cyclins during tumorigenesis outweighing reduced antiproliferative Crol effects." (PMID 39762218, 2025). "Moreover, EGF upregulates αMβ2 integrin on TAMs and ICAM-1 on tumor cells." (PMID 41280929, 2025). "The tumour TME has a direct effect on the immune response of cells and involves the expression and activity of cytokines, such as interleukins, interferons and growth factors, like transforming growth factor (TGF)-β, vascular endothelial growth factor and epidermal growth factor (EGF)." (PMID 40365251, 2025). "Additionally, MDSCs release IL-6, TGF-β, EGF, and HFG, promoting EMT in tumor cells." (PMID 38732051, 2024). "Epidermal growth factor (EGF) is highly expressed in tumor, rather than normal, ECs." (PMID 38892305, 2024). "The expression levels of EGF-EGFR-RAS signaling marker genes EGF, EGFR, HRAS, RASSF1 and STK4 in the HLX22 and HLX02 combination-treated cells decreased, suggesting that HLX22 in combination with HLX02 inhibited EGF-EGFR-RAS signaling to suppress tumor proliferation, survival, and invasion." (PMID 38982548, 2024). "In addition, based on keyword co-occurrence analysis, the research trend has gradually evolved from the role of epidermal growth-induced controversy (EGF) and vascular endothelial growth factor (VEGF) in the TME to how antivascular therapy plays an important role in the tumor treatment process." (PMID 39691714, 2024). "During tumour progression, TAMs may be more inclined to the M2 polarized state and can secrete various growth factors such as VEGF, PDGF, EGF, chemokines and cytokines such as IL-10, TGF-β, CCL2 and CXCL12; thus, the tissue trophic function of M2-type TAMs instead promotes tumour progression." (PMID 39060648, 2024). "In addition, in terms of structure and function, CAFs can provide a fertile environment for tumor growth by secreting extracellular matrix ECM protein, epidermal growth factor (EGF)/fibroblast growth factor, pro-angiogenic factor, platelet-derived growth factor (PDGF), chemokines and other factors." (PMID 39679376, 2024).
tumor (continued). "Despite the fact that the absolute number of CD117+CD44+, CD117+EGF+ and CD117+EGF+CD44+ cells did not increase in tumor formation, the relative content of Sox2+ cells in these populations was significantly higher compared to similar indicators in intact animals." (PMID 38664641, 2024). "Overall, we show that EGF may activate an EGFR-mediated signaling pathway through p38β MAPK, to upregulate the invasion factor ODZ1, which may initiate morphological changes for tumor cells to invade the surrounding parenchyma." (PMID 38727302, 2024). "CD109 influences key inflammatory pathways, including TGF-β/NF-κB, EGF/STAT3, and various inflammatory cytokines like IL-6 and IL-8, impacting inflammatory processes such as immune cell recruitment, macrophage polarization, immune microenvironment, EMT, and tumor progression." (PMID 39990858, 2024). "Hence, the presence of EGF in the analyzed human serum samples most likely does not account for the observed protective effect on tumor cells." (PMID 39403185, 2024). "Upon binding of EGF or other ligands, EGFR is activated and induces the activation of downstream signaling pathways, including Ras-MAPK, PI3K/Akt, JAK/STAT, and PLCγ/PKC pathways, which leads to tumor cell proliferation, angiogenesis, tumor invasion, metastasis, and inhibition of apoptosis." (PMID 37974093, 2023). "The knockdown of NANOG in the cisplatin-resistant tumor cells led to a significant decrease in autophagosome abundance, EGF secretion and the level of pEGFR, suggesting an important role of NANOG in regulating the autophagy-mediated EGFR activation of cisplatin-resistant tumor cells." (PMID 37165076, 2023). "However, a proangiogenic effect of 11,12-EET and 14,15-EET, the main EET regioisomers in mammals, has been described via the epidermal growth factor (EGF) and VEGF pathways, which may explain the finding that EETs promote tumor growth." (PMID 36937889, 2023). "Moreover, we have shown that the EGF-QD complex effectively binds to cells overexpressing the EGF receptor, which is often observed in tumor cells of various origins but not in normal cells with low receptor density." (PMID 36769021, 2023). "In tumour aggressive growth and proliferation, the contribution of angiogenesis is enormous, and promoting factors include VEGF, bFGF, angiogenin, granulocyte colony-stimulating factor (GCSF), EGF hepatocyte growth factor, platelet-derived growth factor (PDGF) and cytokines." (PMID 38203605, 2023). "The high radioactivity could be significantly reduced by injection of unlabeled EGF before treatment, without interfering with radioactivity of the tumor target." (PMID 37746282, 2023). "Moreover, there are many growth factors involved in tumor angiogenesis, such as vascular endothelial growth factor (VEGF), epidermal growth factor (EGF), angiogenin (Ang), fibroblast growth factor (FGF), platelet-derived growth factor (PDGF), TNF-α and placental growth factor (PLGF)." (PMID 38298540, 2023). "Our data suggest that in precancerous states and to prevent tumour relapse, EGFR activation—such as through EGF treatment—might provide a competitive advantage to wild-type cells in the presence of neighbours expressing the constitutively active form of a Ras oncogene." (PMID 37344586, 2023). "We hypothesized that this tumor growth is accelerated and mediated by a constant loop-like transcription or translation regulation of effector genes of the growth factor family: NGF, NT3/4, EGF, and PDGF." (PMID 37965463, 2023). "Moreover, it has been reported that inhibiting SLC1A5 can promote the degradation of epidermal growth factor through the UPS pathway and reduce the expression of epidermal growth factor in the nucleus to help improve the sensitivity of drugs to tumor treatment." (PMID 37190313, 2023). "Furthermore, A study showed that epidermal growth factor (EGF) can stabilize PD-L1 expression and an EGF inhibitor (gefitinib) might enhance anti-tumor immunity in syngeneic mouse models." (PMID 36539510, 2023).
tumor (continued). "Therefore, we tested whether our BiXAbTM could block EGF/NRG1-induced AKT and ERK phosphorylation in six tumor cell lines." (PMID 37153618, 2023). "Unlike other tumor organoids, removal of EGF and adding of Wnt inhibitors could achieve better success rate in the culture of pancreatic cancer organoids." (PMID 37576596, 2023). "In addition, YAP/TAZ can regulate the production of secretory proteins, such as amphiregulin (AREG; an epidermal growth factor (EGF) family member), cysteine-rich angiogenic inducer 61 (CYR61), and connective tissue growth factor (CTGF), to influence the tumor microenvironment." (PMID 35701841, 2022). "In recent cancer therapy advances, tumor angiogenesis became a target, whereby a range of angiogenic factors, such as vascular endothelial growth factor (VEGF), insulin-like growth factor-1 (IGF-1), platelet-derived growth factor (PDGF), and epidermal growth factor (EGF), are inhibited." (PMID 36555410, 2022). "Additionally, for the ceRNA crosstalk pair MAPK1–CCNNB1, studies found that EGF-induced activation of ERK (MAPK1) could promote β-catenin (CCNB1) transactivation and tumor cell invasion." (PMID 35433687, 2022). "Among them IL-1, IL-6, epidermal growth factor (EGF) help tumor cells survive, VEGF and IL-8 promote angiogenesis, M2 macrophages, and MDSCs antagonize inflammatory responses, IL-10, TGF-β, C-C motif chemokine ligand (CCL17) inhibits tumor immune function, and TGF-β and MMP promote tumor metastasis." (PMID 36686745, 2022). "Several oncogenes and tumor suppressor genes, including Myc, epidermal growth factor (EGF), phosphoinositol three kinase (PI3K), mTOR, and hypoxia-inducible factor 1α (HIF-1α), are involved in the metabolic switch from oxidative phosphorylation (OXPHOS) toward altered glycolysis of tumor cells." (PMID 35873566, 2022). "Although EGF : EGFR interaction is essential for normal maintenance and renewal of epithelial cell populations, the overexpression and hyperactivation of EGFR contributes to tumor progression, rendering it an important biomarker and target for anticancer therapeutics." (PMID 36591314, 2022). "Considering our results that TSPAN6 had no apparent effect on EGFR-induced proliferation but markedly altered invasive behavior in response to EGF, TSPAN6-regulated cell polarity and an EMT could conceivably explain why the modulation of TSPAN6 expression affects metastatic tumor spread." (PMID 35184157, 2022). "Tumor-derived factors such as colony-stimulating factor 1 (CSF1; also known as M-CSF), granulocyte-macrophage colony-stimulating factor (GM-CSF), CC-chemokine ligand 2 (CCL2), CCL7 (or MCP-3), GDNF, IL-33, CXCL12 (SDF-1) and EGF are responsible for myeloid cell recruitment and promote tumor growth." (PMID 36140392, 2022). "An interesting possibility would be to look for variants of EGF, HGF, IGF-1, and VEGF as has already been done with other molecules; this would foster the regeneration process or at least not hinder it, without affecting tumor progression." (PMID 34572344, 2021). "Similar to 2D cultures, EGF did not induce significant EGFR degradation in 3D-cultured tumor cells." (PMID 34572731, 2021). "Tumor tissue maintains a continuous pro-angiogenic state by increasing the expression of a series of pro-angiogenic factors, such as VEGF, Ang 2, epidermal growth factor (EGF) and platelet-derived growth factor (PDGF), to fulfill their increased demand for nutrients and oxygen." (PMID 34930293, 2021). "It was reported that the EGF-EGFR pathway was involved in the development of inflammatory microenvironment in HCC; EGF might facilitate DNA synthesis, regeneration, tumor growth, and progression of HCC cells and bind with EGFR as the potential connection between inflammation and HCC." (PMID 33688369, 2021).